CGA (glycoprotein hormones, alpha polypeptide)
Diseases named in the same sentence as CGA in open-access papers (continued):
Sharing a sentence is not in itself a finding about the gene and the disease.
tumor (continued). "Daily administration (i.v.)of 0.06 μg of VS-1 (i.e. a dose equivalent, on a molar basis, to the bioactive dose of full-length CgA) exerted anti-tumor effects similar to those induced by full-length CgA." (PMID 27203389, 2016). "CgA is more frequently elevated in well-differentiated tumours compared to poorly differentiated tumours." (PMID 26911576, 2016). "A growing body of evidence suggests that CgA and its N-terminal fragment 1-76, called vasostatin-1 (VS-1), can also have a role in tumor biology." (PMID 27203389, 2016). "Vasostatin-1, one of the most widely studied CgA fragments, inhibits tumor angiogenesis, apparently by inhibiting the endothelium-stimulatory effects of hypoxia and tumor-secreted factors." (PMID 25785244, 2015). "In mice, CgA inhibits transit of mammary cancer cells among primary tumor, blood, and organ compartments." (PMID 25785244, 2015). "Mechanistically, CgA inhibits tumor cell-induced formation of endothelial gaps and decreases TNFα-induced vascular leakage, reduces vascular leakage within tumors, and inhibits tumor cell transendothelial migration." (PMID 25785244, 2015). "In tumor biopsies from patients with advanced PCa (stage D2), strong CgA immunostaining was correlated with higher 2-year recurrence rates and much shorter time to recurrence." (PMID 25785244, 2015). "Overall, the NET index was more sensitive than CgA in identifying neuroendocrine lesions and elevation was evident prior to image-based tumor confirmation in this patient." (PMID 25095873, 2014). "We also examined the relevance of combining the measurement of WE-14, CgA and EM66, in comparison to CgA alone, for the potential improvement of the diagnostic sensitivity for this tumor." (PMID 24523932, 2014). "In our observation, tumor cells positive for CgA, Syn, or both were scattered or focally clustered in most of the tumors." (PMID 25093184, 2014). "Using samples from our present tumor cohort, we found that the sensitivity of the CgA test was identical to that of WE-14." (PMID 24523932, 2014). "Previous studies have shown that levels of CgA vary with the degree of differentiation and tumor burden." (PMID 25501094, 2014). "One of them was small cell NEC, with only focal expression of CgA and synaptophysin and with high proliferative activity of tumour cells (Ki-67 index exceeding 50%), corresponding with G3." (PMID 24695372, 2014). "All tumours showed strong immunostaining for CgA and synaptophysin in the majority of neoplastic cells and displayed very low proliferative activity corresponding with G1 (Ki-67 index ≤2)." (PMID 24695372, 2014). "The NET Index was elevated from initial visit (December 2008) when residual tumor was evident by imaging (CgA was normal)." (PMID 25095873, 2014). "CgA can also be used as a tumor development biomarker and for evaluating prognosis during clinical applications." (PMID 25523133, 2014). "With cutoff values of 10 or 20 Syn- and/or CgA-positive tumor cells per HPF, Kaplan-Meier survival analysis showed that there was no survival difference between stage II Group 1 and Group 2 (P = 0.155, 0.340, resp)." (PMID 25093184, 2014). "Kaplan-Meier survival analysis showed that there was no survival difference between stage II Group 1 and Group 2 with cutoff values of 10 or 20 Syn- and/or CgA-positive tumor cells per HPF, respectively." (PMID 25093184, 2014). "In this case, the tumor cells were positively stained for CgA and Syn (the immunological markers for tumors derived from the neuroendocrine system) and negatively stained for AFP." (PMID 25120653, 2014). "Unfortunately, clinicians are, to a large extent, unaware of such limitations and that CgA is only a moderately effective GEP-NET tumor biomarker." (PMID 25316294, 2014). "Chromogranin A (CgA) was considered as the most practical and useful serum tumor marker in PNET patients." (PMID 25099181, 2014).
tumor (continued). "In recent ENETS and NANETS consensus guidelines, CgA was considered as the most practical and useful serum tumor marker in PNET patients." (PMID 25099181, 2014). "When ≥1 tumor cells/HPF (high power field) were positive for CgA and/or Syn, the tumor was designated as NED(+)." (PMID 25093184, 2014). "It is more accurate than the currently used clinical standard CgA assay, which identifies a single peptide related only to tumor secretion." (PMID 23691035, 2013). "Another option is a somatostatin analogue, such as octreotide, which reduces tumour number and size, reduces serum gastrin concentrations indirectly, and reduces circulating chromogranin A (CgA), which is a marker of ECL-cell mass and activity." (PMID 24098507, 2013). "We also examined the effect of CgA silencing and pharmacologic inhibition of prohormone convertase on tumor cell proliferation, secretion and post-transcriptional changes in CgA fragment expression." (PMID 24260544, 2013). "That conclusion is strengthened by a subsequent study in patients with multiple type 1 gastric NETs, which also showed that netazepide reduces tumour number and size and normalises serum CgA." (PMID 24098507, 2013). "Strategies including staging at surgery, pathological grading, blood Chromogranin A (CgA) measurements, detection of circulating tumor cells (CTCs) or other products e.g. serotonin are currently used." (PMID 23691035, 2013). "Currently, CgA is used to evaluate treatment protocols as expression levels are considered to relate to tumor burden." (PMID 23691035, 2013). "The reductions in abundances, circulating CgA, and tumour number and size by netazepide, a gastrin receptor antagonist, show that type 1 gastric NETS are gastrin-dependent tumours." (PMID 24098507, 2013). "CgA sensitivities (number of patients with median CgA values above reference range/number of all patients of the corresponding group) depending on tumor primary." (PMID 24213232, 2012). "In 15 of the 32 tumours, some tumour cells were positive for one or more neuroendocrine markers, CgA and serotonin in five cases." (PMID 22474435, 2012). "Our aim was to assess the sensitivity of CgA depending on tumor primary location and the existence of liver and additional extra-hepatic metastases." (PMID 24213232, 2012). "Plasma chromogranin A (CgA) is a widely accepted tumour marker with respect to diagnosis, prognosis, and monitoring of the treatment." (PMID 22319653, 2012). "One patient had linear hyperplasia and micronodules positive for HDC and CgA in mucosa adjacent to the tumour." (PMID 22474435, 2012). "In NEN regional lymph nodes, CgA transcripts (77%, 47/61) were detected significantly more frequently than tumor cells on H&E staining (54%, 33/61) or CgA protein (56%, 34/61) on IHC staining (p = 0.02, post-hoc testing H&E vs PCR significant)." (PMID 22720672, 2012). "Slides assigned to CgA PCR were processed by scraping tumor tissue from unstained paraffin embedded slides and RNA extracted using QuickExtractTM FFPE RNA Extraction Kit (Epicentre Biotechnologies, Madison, WI)." (PMID 22720672, 2012). "In consideration of the slow tumor progression, the low Ki-67 labelling index and the expression of CgA and synaptophysin, the diagnosis was ultimately changed to TC." (PMID 22269186, 2012). "CgA sensitivities in NETs classified in pancreatic and midgut NETs depending on tumor primary and assay (CIS-bio IRMA kit, DAKO ELISA kit, in-house RIA)." (PMID 24213232, 2012). "The level of transcript expression was correlated with the degree of tumor involvement of lymph nodes across all three CgA primers, with higher levels of CgA expression seen in lymph nodes with majority or complete replacement by NEN." (PMID 22720672, 2012). "Chromogranin A (CgA) has replaced the 24-h urine collection of 5-hydroxyindoleacetic acid and has become the most important tumour marker in the monitoring of NET during and after treatment and is recommended by the European NeuroEndocrine Tumor Society." (PMID 21989216, 2011).
tumor (continued). "Increased CgA levels in blood is the standard biomarker and considered important in indicating tumor recurrence in most radically operated midgut carcinoid tumor patients." (PMID 21209860, 2010). "Circulating CgA is considered important in indicating tumor recurrence in most radically operated midgut carcinoid tumor patients." (PMID 21209860, 2010). "Fairly strong CCN2 immunoreactivity was found in CgA positive (tumor) tissue obtained from both the gut and from the liver." (PMID 20053285, 2010). "Predicting the behaviour of NETs in individual cases has to date relied on tumour histology, serum CgA levels, and serial radiology imaging." (PMID 18577995, 2008). "Plasma chromogranin A (CgA) has been claimed the most sensitive and specific marker of tumour volume." (PMID 16800893, 2006). "The tumour cells were positive for the general NE-marker CgA, serotonin (5-HT) and Vesicular Mono Amine Transporters (VMAT1 and 2)." (PMID 16251870, 2005). "A total of 118 human endocrine and nonendocrine tumours were examined by immunocytochemistry, and compared to the expression of chromogranin A (CgA) in the same tumours." (PMID 12771991, 2003). "Among six patients with NET followed for 11-37 months, CgA appeared to be a better marker of tumour evolution than NSE." (PMID 9792158, 1998). "The tumor marker CgA decreased significantly at 3 months (1424.3 vs. 2650.7 ng/ml, p = 0.05)." (PMID 40202686, 2025). "Therefore, the change of CgA level cannot reflect the progress of tumor, and thus cannot be correlated with survival outcome." (PMID 39975592, 2025). "Immunostaining showed that the tumor was neuroendocrine, as they were positive for Chromogranin A (CgA), Synaptophysin (Syn), CD56, CK, CK7, CK8, Epithelial membrane antigen (EMA), Recombinant Somatostatin Receptor 2(SSTR2), insulinoma-associated protein 1(INSM1), KI-67 was 70 %." (PMID 40034377, 2025). "Abdominal contrast-enhanced CT demonstrated a characteristic mesenteric mass, and immunohistochemical analysis of tumor tissue revealed positive staining for CgA and synaptophysin, with a Ki-67 proliferation index ranging from 3% to 20%, thereby classifying it as G2." (PMID 40324239, 2025). "Our data hence provide initial insights into an immunoregulatory mechanism via miR-223 and CgA in NEN cells, as regulation of miR-223 in NEN may affect tumor-associated inflammation." (PMID 39851539, 2025). "CgA has a regulatory effect on immune cells in the tumor microenvironment." (PMID 39975592, 2025). "European Society for Medical Oncology practice guidelines mandate histological diagnosis in all the patients and suggest the reporting of morphology, grading, and immunohistochemical staining of chromogranin A (cgA) and synaptophysin for appropriate pathological diagnosis of the tumor." (PMID 41235383, 2025). "In addition, treatment with somatostatin analogs (SSAs) affects CgA levels, making it difficult to use as a reliable marker of tumor mass." (PMID 38928704, 2024). "Using the prespecified cut-off of CgA change for tumor progression, specificity was 93.4% (95% confidence interval, 90.4%–95.5%; P < 0.001), sensitivity 34.4% (25.6%–44.3%), positive predictive value 57.9% (45.0–69.8), negative predictive value 84.3% (80.5–87.6), and AUC 0.73 (0.67–0.79)." (PMID 39453770, 2024). "The increased level of CgA in NENs releasing this peptide may correlate with the tumor mass and recurrence, and it is considered a marker of poor prognosis and shorter survival in patients with GEP-NENs." (PMID 39451760, 2024). "Gal-3 and CgA showed the lowest levels in both tumor regions." (PMID 39195201, 2024). "Histopathological examination of the biopsy sample is necessary to confirm the neuroendocrine nature of the tumor, usually characterized by uniform cells with neuroendocrine differentiation on immunohistochemical staining, positive for markers such as CgA and synaptophysin." (PMID 39233931, 2024).
tumor (continued). "Additionally, a positive correlation was found between CgA levels and several inflammatory cytokines, suggesting their synergistic role in tumor progression." (PMID 39451760, 2024). "In general, follow-up may include physical examinations, laboratory tests (mainly the tumor markers CgA and 5-HIAA) and imaging studies with abdominal US, CT or MRI, and, if clinically indicated, Octreoscan." (PMID 39456535, 2024). "The gradual increase in the CgA concentration in the long-term observation may result from the return of secretory function of tumor cells or the manifestation of a renewed growth of the lesions." (PMID 39456603, 2024). "Nevertheless, other studies have identified specific clinicopathological characteristics that can predict an adverse prognosis for SCNCC patients, including a tumor diameter of >4 cm, deep stromal invasion (>2/3), positive parametrial invasion, positive resection margins, and positive CgA." (PMID 38793044, 2024). "Chromogranin A (CgA) is the most often used tumor marker in NENs of lung origin." (PMID 37444393, 2023). "Few studies interrogated the role of CgA to predict tumor recurrence." (PMID 37685358, 2023). "Additionally, as CgA correlates with both tumor burden and biological activity, it is a predictive factor for midgut carcinoids." (PMID 37568540, 2023). "The greatest limitation of our study is its single-center retrospective cohort nature, which resulted in the restricted availability of clinical data on patients’ symptoms (abdominal pain, jaundice, weight loss, etc.), and tumor marker findings (CEA, CA19-9, CgA)." (PMID 37685379, 2023). "An observed decrease of CgA in the study group (as well as in both subgroups: 177-Lutetium vs. 177-Lutetium and 90-Yttrium) correlated with clinical and imaging results, confirming the stabilization or regression of the tumor." (PMID 37765013, 2023). "Indeed, SCNECs and MCCs are histologically similar, with both tumor types staining for neuroendocrine markers, such as synaptophysin and CgA." (PMID 38137784, 2023). "CgA levels are influenced by tumor cell type and histologic differentiation." (PMID 37190177, 2023). "When interpreting CgA data, it is crucial to consider both the tumor load and secretory activity." (PMID 37568540, 2023). "Serum CgA level was a reliable tumour marker during follow-up." (PMID 36923225, 2023). "Furthermore, CgA seems to have a prognostic role since it has been reported to be closely related to the degree of tumor differentiation and tumor burden." (PMID 37627093, 2023). "Circulating CgA has been correlated with tumor burden, progression, and metastasis." (PMID 37685358, 2023). "Finally, the NETest was able to predict tumor recurrence with 94% accuracy compared with CgA after surgery." (PMID 37685358, 2023). "Additionally, NETest showed a better correlation with other clinical parameters (i.e., imaging, tumor grade, Ki67 index) compared with CgA with an accuracy of >91% versus <50%, respectively." (PMID 37685358, 2023). "In addition to tumor-derived variables, continuous variables such as age, plasma CgA, and urinary 5-HIAA are used in the nomograms." (PMID 35626155, 2022). "Many publications indicate that the dysregulated release of CgA by neuroendocrine cells may affect the components of the tumor stroma, contributing to the regulation of tumor growth or progression." (PMID 36289922, 2022). "Moreover, CgA concentration correlates with tumor burden; the highest values are observed in metastatic NETs, in which the specificity of 100% and sensitivity between 78 and 80% have been reported." (PMID 36233409, 2022). "For example, CgA is a commonly used marker to confirm a neuroendocrine origin of the tumour." (PMID 36362433, 2022). "CgA, Ki67 index, and tumor stage IV were also significant in the multivariate analysis (p ≤ 0.05)." (PMID 35837305, 2022).
tumor (continued). "It is therefore tempting to speculate that changes in the relative levels of these protease/anti-protease molecules in tumor lesions represent a major mechanism for the regulation of the CgA-dependent angiogenic switch." (PMID 36559048, 2022). "CgA concentration correlates with tumor burden; the highest values are observed in metastatic NETs." (PMID 36233409, 2022). "Immunohistochemistry evaluation showed CD57+, Syn+, and CgA− tumor cells." (PMID 35873475, 2022). "Primary tumor, ECOG status, functional tumor, tumor grade, and baseline CgA level were neither associated with the amount of decrease in TL-SSTR or SSTR-TV, nor with time-to-new treatment, when tested individually." (PMID 34881405, 2021). "An increase of CgA level greater than 40% of the CgA level in the follow-up after treatment may predict tumor progression." (PMID 34868938, 2021). "Serum CgA is related to tumor burden, and the serial measurement of CgA may be useful to detect recurrence." (PMID 34572940, 2021). "Our study results suggest that CgA may be a predictive marker for tumor burden, OS, and tumor progression in GEP-NET patients." (PMID 34868938, 2021). "A sudden increase in serum CgA was accompanied by rapid tumor growth and short survival." (PMID 33485291, 2021). "The tumor cells were positive for CT, CgA, Syn, CD56, and TTF-1 in all 4 cases." (PMID 34838061, 2021). "CgA can be a surrogate of tumor burden, which has prognostic impact." (PMID 33903926, 2021). "A 40% or greater increase of CgA level during follow-up might be a predictive factor for tumor progression or recurrence of GEP-NETs." (PMID 34868938, 2021). "A 40% or greater increase of change of CgA level may predict tumor progression or recurrence during treatment or surveillance of GEP-NETs." (PMID 34868938, 2021). "In addition, in the lanreotide group, 17.4% of patients had an objective tumor response, 35.5% of patients had a variable degree of tumor shrinkage, 65.2% patients had a stable disease, and 100% of patients normalized baseline CgA levels." (PMID 32121432, 2020). "Contaminating stromal cells may mask the actual expression of cGAS-STING, or this difference reflects both pro-tumor and anti-tumor roles of cGA-STING in specific tumor types." (PMID 32571374, 2020). "Furthermore, the high incidence of antacid introduction after tumor diagnosis prevented us from comparing postoperative CgA level of patients with preoperative measurements, therefore, further studies are recommended to clarify these questions." (PMID 33383764, 2020). "Furthermore, a sudden increase in serum CgA was accompanied by rapid tumor growth and short survival." (PMID 32020844, 2020). "Because of its potential pathophysiological function in the regulation of tumor biology and growth, CgA may represent a potential therapeutic target that warrants further exploration." (PMID 33425767, 2020). "A further study for comparative CgA levels of tumor tissue and serum CgA levels in Pan-NETs is warranted to prove possible feasibility of CgA immunostaining to distinguish benign Pan-NETs and other NETs from malignant counterparts for initial diagnosis and clinical follow-ups." (PMID 32020844, 2020). "Finally, administration of full-length CgA to mice bearing orthotopic PDAC reduced tumor perfusion, as measured by contrast-enhanced ultrasound." (PMID 33425767, 2020). "In addition, we further analyzed the heterogeneity of CgA, Syn, and the Ki-67 index according to the primary tumor site, and found that these markers differed between the primary and metastatic sites." (PMID 32917216, 2020). "Finally, we investigated the effect of exogenous CgA on tumor vasculature and perfusion using DT6606 PDAC cells implanted orthotopically in the pancreas of syngeneic mice." (PMID 33425767, 2020).